TNF (tumor necrosis factor)
Diseases named in the same sentence as TNF in open-access papers (continued):
Sharing a sentence is not in itself a finding about the gene and the disease.
celiac disease (43 papers, 1995 to 2025). An autoimmune genetic disorder with an unknown pattern of inheritance that primarily affects the digestive tract. "Larger longitudinal studies integrating additional cytokines and signaling pathways are needed to clarify the role of TNF-α in bone loss in celiac disease." (PMID 41141340, 2025). "For one thing, significantly higher levels of M1-associated pro-inflammatory cytokines, i.e., IFN-γ, IL-1β, TNF-α, and IL-8 have been identified in celiac disease sera." (PMID 31178867, 2019). "Archaea has a strong pro-inflammatory effect and a strong correlation with TNF-α, which may be a risk factor for coeliac disease." (PMID 39166131, 2024). "In the group of patients with celiac disease and normal bone mass (group B), there is expected inverse relationship between the level of TNF-α expression and bone parameters, which is consistent with the known pro-resorptive effect of TNF-α on bone." (PMID 41141340, 2025). "IL1β levels are increased in celiac disease, and together with TNF and IFNG, it favours intestinal permeability, a characteristic feature of celiac disease." (PMID 37175481, 2023). "TNF-α, as a pleiotropic cytokine, has been shown to correlate with numerous intestinal diseases such as active celiac disease and IBD." (PMID 35756539, 2022). "Verrucomicrobia are common in the colonic microbiota, and their abundance has been shown to positively correlate with TNF-α levels in patients with celiac disease." (PMID 35680568, 2022). "Increased expression of toll-like receptor 2 (TLR-2) and 4 (TLR-4), claudin 4 (CLD-4), and TNF-α has been shown by different groups in subjects with self-reported gluten intolerance." (PMID 33297984, 2020). "In fact, patients carrying the rare G allele have been suggested to synthesize a truncated TNFR-1, and the common A allele was previously demonstrated by us to be correlated with increased serum TNF-α levels in patients with celiac disease." (PMID 29579081, 2018). "Our aim in this study was to determine soluble tumor necrosis factor (TNF)-like weak inducer of apoptosis (sTWEAK) and interleukin-17A (IL-17A) levels in celiac disease, and their association with the gluten diet and autoantibodies." (PMID 27367991, 2016). "In our study, the median value of TNF-α was lower in coeliac disease compared to controls, which has been shown in a former study of cytokine production in intestinal T cells in coeliac disease." (PMID 25212572, 2015). "In anecdotal cases, monoclonal antibodies against TNF-α (infliximab) has been shown to be beneficial for patients with severe refractory celiac disease and refractory celiac disease." (PMID 25705619, 2014). "The high levels of TNF-α and IFN-γ association with patients with CD and MC as compared with controls is reminiscent of that described in mucosa of patients with celiac disease." (PMID 23613969, 2013). "Therefore, our study aimed to investigate the impact of TNF-α gene expression on bone mineral density in patients with celiac disease." (PMID 41141340, 2025). "Moreover, several studies demonstrate that B. breve strains, in combination with a gluten-free diet (GFD), temporarily reduce TNF-α production in children with celiac disease, thereby counteracting the pro-inflammatory environment." (PMID 40207278, 2025). "This systematic review also suggested that probiotic preparations may improve the intestinal flora and reduce the level of TNF-α in patients with celiac disease." (PMID 38475833, 2024). "Parcubacteria may be responsible for the development of celiac disease in children, since the abundance of Parcubacteria was strongly correlated to serum tumor necrosis factor alpha (TNF-α) in children with celiac disease." (PMID 36365048, 2022). "More specifically, gliadin peptides could induce significantly higher levels of IL-8 and TNF-α production by Mo from patients with celiac disease relative to those from healthy donors." (PMID 31178867, 2019).
celiac disease (continued). "Intriguingly, even in patients with celiac disease on a gluten-free diet whose duodenal biopsy specimens are histologically normal, intraepithelial lymphocytes and intestinal epithelial cells exhibit increased expression of TNF-α and MIF." (PMID 31178867, 2019). "A recent Italian report has described a combined effect of -1082 and TNF-308A polymorphism in celiac disease, but although in our population an effect of the TNF-308A polymorphism does exist, we do not observe an interaction between both genes." (PMID 16579847, 2006). "Reducing TNF-α could decrease the intestinal and systemic complications of celiac disease." (PMID 40207278, 2025). "However, no studies to date have focused on the association between TNF-α gene expression and altered bone parameters in patients with celiac disease." (PMID 41141340, 2025). "This speculation would be in line with a previous finding of significantly higher levels for IL-6, IL-13, IL-10, IL-1b, and TNF-α in combination with significantly lower 25(OH)D concentrations in screening-detected celiac disease cases compared with healthy controls." (PMID 34604278, 2021). "In celiac disease, gliadin peptides activate CD4+ T cells, triggering release of pro‐inflammatory cytokines (TNF‐α, IFN‐γ, IL‐8) that parallel the cytokine cascade seen in PRES‐associated conditions." (PMID 40114993, 2025). "For example, Neisseria flavescens isolated from the duodenum of patients with celiac disease can escape the degradation of lysosomes in Caco-2 cells and directly induce dendritic cells to release inflammatory factors such as INF-γ and TNF-α." (PMID 38475833, 2024). "The study showed a significant increase in several cytokines including TNF-α, IFN-γ, IL-6 and IL-10: all crucial in the pathogenesis of celiac disease." (PMID 25326000, 2015). "The increase in both paracellular and transcellular permeability observed during active celiac sprue is due, at least in part, to the Th1 cytokines interferon-γ (IFN-γ) and tumor necrosis factor α (TNF-α)." (PMID 18425213, 2008). "TNF-α and IFN-γ play a role in the development of mucosal damage in celiac disease (CD)." (PMID 25915602, 2015). "One study found that patients with celiac disease who tested positive for tTg-IgA had significantly higher levels of pro-inflammatory cytokines, including IFN-γ, TNF-α, and IL-6, compared to patients without tTg-IgA." (PMID 39697959, 2024).
oral squamous cell carcinoma (43 papers, 2012 to 2025). "For example, tumour regression or resistance in oral squamous cell carcinoma has been associated with dynamic variations in IL-8 or TNF-α levels throughout therapy." (PMID 41245374, 2025). "Tumor necrosis factor alpha secreted from oral squamous cell carcinoma contributes to cancer pain and associated inflammation." (PMID 39050547, 2024). "Polymorphisms affecting the gene expression of TNF-α have been strongly associated with an increased risk for oral squamous cell carcinoma." (PMID 36980727, 2023). "ALPK1-deficient oral squamous cell carcinoma metastasis leads to reduced TNF-α production in cancer cells." (PMID 36139553, 2022). "We found that increased salivary concentration of IL-17A, IL-17F, and TNF-α is associated with advanced oral squamous cell carcinoma." (PMID 32855976, 2020). "Researchers studied several salivary protein biomarkers that can be used for the detection of oral squamous cell carcinomas, such as Interleukin-6 (IL-6), Interleukin-8 (IL-8), and tumor necrosis factor-alpha (TNF-α), to name a few." (PMID 40096419, 2025). "The concentrations of TNF-α, IL-8, and IL-6 in human saliva and serum progressively increased from healthy individuals to oral leukoplakia patients and finally to oral squamous cell carcinoma (OSCC) patients (P < 0.05)." (PMID 41415031, 2025). "The enhancement of the CSC-like phenotype in oral squamous cell carcinoma cells by tumor necrosis factor-α (TNFα) is due to NOTCH1 activation." (PMID 39547513, 2024). "TNF-α is of interest in oral squamous cell carcinoma (OSCC), with its demonstrated presence affecting both tumour and stromal inflammatory cells to enhance proliferation and facilitate invasion." (PMID 36980727, 2023). "Studies have shown that IFIT2 depletion can lead to up-regulation of TNFα promoting angiogenesis, metastasis, epithelial-mesenchymal transition, cell migration, and invasion of oral squamous cell carcinoma." (PMID 37046696, 2023). "Studies have demonstrated that there is an increased level of TNF-α and inflammatory cytokines in oral squamous cell carcinoma compared with premalignant lesions or undifferentiated oral leukoplakia." (PMID 36980727, 2023). "Higher levels of tumor necrosis factor (TNF-α) have been found in oral squamous cell carcinoma (OSCC) than in controls, and even in premalignant lesions, significant differences are noted between patients with early-stage OSCC and controls." (PMID 36330456, 2022). "For example, TNF-α was proved to promote invasion and metastasis by the NF-κB pathway in oral squamous cell carcinoma." (PMID 35873484, 2022). "In the pathogenesis of oral squamous cell carcinoma, TNF-α can regulate EMT through the MAPK signaling pathway to promote cancer cell invasion and metastasis, and DOK5 also involved in MAPK (mitogen-activated protein kinase) signal pathway activation." (PMID 35036444, 2022). "Further investigations are recommended to validate the use of TNF-α and cellular micronuclei as salivary biomarkers for early diagnosis of oral squamous cell carcinoma." (PMID 34299679, 2021). "Increased levels of TNF-α in both the saliva and serum in patients with oral squamous cell carcinoma compared to a healthy control group have been reported." (PMID 32855976, 2020). "TNF-α is suggested to be a marker of oral squamous cell carcinoma, and its concentration has been showed to be higher in the saliva than in plasma due to high local cytokine production." (PMID 32855976, 2020). "TNF-α secretion, leading to angiogenesis and metastasis of oral squamous cell carcinoma, can be regulated by IFIT2 depletion." (PMID 30875792, 2019). "Taking together, our results suggest that Wnt/β-catenin signal pathway activation-dependent up-regulation of syncytin-1 contributes to the pro-inflammatory factor TNF-α-enhanced fusion between oral squamous cell carcinoma cells and endothelial cells." (PMID 28112190, 2017).
oral squamous cell carcinoma (continued). "In the present study, we show that the pro-inflammatory factor TNF-α can activate Wnt/β-catenin signal pathway and thereby enhance the fusion between oral squamous cell carcinoma cells and endothelial cells via up-regulation of fusogenic protein syncytin-1." (PMID 28112190, 2017). "Such mimicry effect has already been shown upon TNF-α (tumor necrosis factor α) stimulation in oral squamous cell carcinoma." (PMID 24107265, 2013). "Macrophages are a likely source of TNF-α within the tumour microenvironment, as supported by the upregulation of genes involved in TNF-α and IL-1β production in macrophages that had engulfed native bacteria in patient colorectal and oral squamous cell carcinoma samples." (PMID 39272829, 2024). "In vitro studies have shown that TNF-α activation of the NF-κB pathway leads to increased protein expression of IKKβ and P65, enhancing the ability of oral squamous cell carcinoma cells to invade through the epithelial basement membrane, and thus increase their ability to metastasize." (PMID 36980727, 2023). "Key words:Salivary cytokines, IL-6, IL-8, TNF-α, oral squamous cell carcinoma, diagnosis." (PMID 37099710, 2023). "For example, the levels of proinflammatory cytokines, including interleukin (IL)-6, IL-8, tumor necrosis factor (TNF)-α, and IL-1β in saliva, have been reported to be elevated in patients with oral squamous cell carcinoma, thus supporting their potential utility as diagnostic biomarkers." (PMID 34884709, 2021). "In this connection, Yan and colleagues also showed that the Wnt/β-catenin-mediated up-regulation of syncytin-1 expression contributed to the tumor necrosis factor-α (TNF-α)-enhanced fusion of human umbilical vein endothelial cells (HUVECs) and oral squamous cell carcinoma (OSCC) cells." (PMID 34207991, 2021). "In addition, salivary TNF is a potential prognostic biomarker for oral squamous cell carcinoma (SCC); moreover, TNF-mediated upregulation of SOD-2 supports cell proliferation and cisplatin resistance in esophageal SCC patients." (PMID 33917839, 2021). "Since chronic inflammation has been suggested to be a cofactor for development of oral squamous cell carcinoma (OSCC) in OLP, the levels of proinflammatory marker TNF-α in OLP patients were evaluated in this study." (PMID 25861271, 2015). "Moreover, oral squamous cell carcinoma cell lines, including HSC2, respond to inflammatory cytokines IL1β and TNFα with an increased expression of chemokines such as CXCL1, CXCL2, CXCL8, and CCL5." (PMID 39199704, 2024). "Moreover, oral squamous cell carcinoma cell lines, including HSC2, respond to inflammatory cytokines IL1β and TNFα with an increased chemokine expression, including CXCL1, CXCL2, CXCL8, and CCL5." (PMID 39199704, 2024). "In oral squamous cell carcinoma, exosomes carrying EBER-1 can induce indoleamine 2,3-dioxygenase (IDO1) expression in monocyte-derived macrophages, with the help of interleukin (IL)-6 and tumor necrosis factor (TNF)-α-dependent mechanisms via the RIG-I signaling pathway." (PMID 36672418, 2023).
graft versus host disease (42 papers, 2015 to 2025). An immune system disorder that occurs after allogeneic hematopoietic stem cell transplant and is a reaction of donor immune cells against host tissues. "In module 4, ribosomes, translation, immune system processes, the TNF signaling pathway, cell adhesion molecules (CMAs) and pathways associated with protein binding, Th1 and Th2 cell differentiation, and graft-versus-host disease were enriched." (PMID 38601160, 2024). "In a graft-versus-host disease model, TNF produced by Tconvs proved to be crucial for Treg responses." (PMID 35844585, 2022). "In this review, we discuss the role of TNF in graft-versus-host disease as an example of the ambivalence of this cytokine in the pathophysiology of an immunopathology, highlighting the therapeutic potential of triggering TNFR2 to boost Treg expansion." (PMID 29593717, 2018). "In human graft-versus-host disease (GVHD) studies, Kordelas and colleagues observed that MSC-exos diminished the production of IFN-γ and TNF-α by activating NK cells." (PMID 40427001, 2025). "The toll-like receptor signaling pathway, TNF signaling pathway, and graft-versus-host disease (not shown) were significantly affected by FMT." (PMID 31963653, 2020). "Additionally, other have used an acute inflammation model, acute graft-versus-host disease (GVHD) mouse model, to document that TNFα in serum selectively activated Treg and induced Treg proliferation and function without impacting CD4+Foxp3− T cells." (PMID 30631042, 2019). "In a study to reduce GvHD (graft versus host disease), MSC-derived exosomes were found to decrease the release of IL1-β, TNF-α, and IFN-γ from PBMCs and the secretion of TNF-α and IFN-γ from natural killer (NK) cells, further confirming their immunosuppressive activities." (PMID 26950273, 2016). "In contrast, SW620 DEGs were characterized by an enrichment in IFN and TNF signaling, ROS and NOTCH pathways (Jagged1, MAML2), but not in graft-versus-host disease or allograft rejection pathways." (PMID 33608544, 2021).
cerebral edema (41 papers, 2011 to 2025). "TBI-induced microglial activation and increased expression of inflammatory mediators (HMGB1, TNF-α, IL-1β, IL-6) in the brain have been associated with cerebral edema and neurological deficits." (PMID 32610502, 2020). "Previous studies have shown that reduced TNF-α and IL-1β caused a marked reduction in ischemic brain damage and cerebral edema." (PMID 24916922, 2014). "After brain injury, the expression of TNF-α, IL-6, IL-1β, and other inflammatory factors is up-regulated, which is closely related to the development of cerebral edema." (PMID 40584448, 2025). "Conversely, in dengue encephalitis, elevated levels of pro-inflammatory cytokines such as TNF-α and IL-1β can contribute to more generalized cerebral edema and hyperintensities in the thalamus and brainstem, often without restricted diffusion." (PMID 39737281, 2024). "In conclusion, our findings revealed altered levels of TNFα, Kir 4.1, GFAP, and AQP4 in HE-associated brain edema." (PMID 36060277, 2022). "TNF-α is recognized as a triggering factor in the immune response of cerebral edema secondary to cerebral hemorrhage." (PMID 35260880, 2022). "Our data show that piperine treatment can reduce the degree of cerebral edema, down-regulate TNF-α, IL-1β, and BDNF, decrease the reactivity of GFAP in the hippocampus, and inhibit TBI-induced seizures." (PMID 32655468, 2020). "We wanted to know if miR-7-5p is also associated with MMP-9, ZO-1, occludin, TNF-α, IL-6, NLR, and CRP and if it jointly affects brain edema." (PMID 33392188, 2020). "Brain TNF-α concentration, microglia activation/macrophage recruitment, hematoma volume, cerebral edema, and rotorod latency were assessed in mice treated with the TNF-α antibody, CNTO5048, or vehicle." (PMID 23962089, 2013). "Many experimental data have revealed that expression of IL-1β and TNF-a increase after ICH, and are associated with brain edema and brain damage." (PMID 24289479, 2013). "Dexamethasone inhibits the production of TNF-α and IL-1β, reduces brain edema, and limits the increase in cerebrospinal fluid lactate and leukocyte concentrations." (PMID 22191010, 2011). "Inflammatory cells release pro-inflammatory cytokines (e.g., TNF-α, IL-1β, IL-6), chemokines, and reactive oxygen species (ROS), which further exacerbate neuronal apoptosis, blood-brain barrier disruption, and cerebral edema, and aggravate neurological deficits." (PMID 41451361, 2025). "As cerebral edema constitutes the main cause of death after IS, this study assessed the therapeutic potential of an emerging strategy, employing hypoxia-primed OEC-CM, in mitigating the previously reported barrier-disruptive effects of TNF-α." (PMID 36056287, 2023). "In contact to excessive TNF-α, EC will also produce matrix metalloproteinase 2 and 9, further disrupting cell–matrix adhesion and contributing to increasing permeability, which can even lead to cerebral edema." (PMID 36970518, 2023). "Furthermore, propofol potentiates neurologic recovery and neurobehavioral outcome through a decrease in myeloperoxidases, nuclear factor (NF)-κB, cyclooxygenase (COX)-2, and TNF-α, which reduces cerebral edema and protects the blood–brain barrier." (PMID 36529842, 2022). "The increase of TNF-α and IL-6 levels may increase the accumulation of Glx in astrocytes and promote the occurrence of cerebral edema." (PMID 34630618, 2021). "Moreover, it inhibited NF-κB DNA-binding activity, reduced expression of inflammatory molecules (TNF-α, IL-1β, IL-6) and ameliorated locomotor function as evident by beam walking performance, along with cerebral edema and cortical apoptotic cell death." (PMID 32610502, 2020). "Plasma TNF-α level has been shown to have direct correlation with brain edema in ICH patients." (PMID 28615993, 2017). "It was suggested that the relationship between NKCC1 and pro-inflammatory cytokines, such as TNF-α and IL-1β, may be one of the key factors of cerebral edema." (PMID 24916922, 2014).